SRSF10 (serine and arginine rich splicing factor 10)
Description:
Splicing factor that in its dephosphorylated form acts as a general repressor of pre-mRNA splicing. Seems to interfere with the U1 snRNP 5'-splice recognition of SNRNP70. Required for splicing repression in M-phase cells and after heat shock. Also acts as a splicing factor that specifically promotes exon skipping during alternative splicing. Interaction with YTHDC1, a RNA-binding protein that recognizes and binds N6-methyladenosine (m6A)-containing RNAs, prevents SRSF10 from binding to its mRNA-binding sites close to m6A-containing regions, leading to inhibit exon skipping during alternative splicing. May be involved in regulation of alternative splicing in neurons, with isoform 1 acting as a positive and isoform 3 as a negative regulator.
Synonyms: SRrp40; TASR; FUSIP1; FUSIP2; SFRS13A; TASR1; TASR2; SRp38; SFRS13; PPP1R149; NSSR
Tractability: PROTAC: its protein half-life has been measured.
Gene: Protein-coding gene on chromosome 1 (23,964,347 to 23,980,927, reverse strand). Ensembl gene ENSG00000188529.
Subcellular location: Nucleus speckle; Cytoplasm
Subcellular location (Human Protein Atlas): Nucleoplasm
Pathways (Reactome):
Metabolism of RNA: Processing of Capped Intron-Containing Pre-mRNA; mRNA Polyadenylation; mRNA Splicing - Major Pathway
Gene Ontology:
Molecular function: protein binding; RNA binding; RS domain binding; nucleic acid binding
Biological process: mRNA splice site recognition; mRNA splicing, via spliceosome; negative regulation of mRNA splicing, via spliceosome; regulation of mRNA splicing, via spliceosome; RNA splicing, via transesterification reactions; regulation of alternative mRNA splicing, via spliceosome; regulation of DNA-templated transcription; spliceosomal tri-snRNP complex assembly; cytosolic transport
Cellular component: nuclear speck; nucleoplasm; cytoplasm; nucleus; axon terminus; cytosol; dendrite; neuronal cell body
Genetic constraint (gnomAD): Loss-of-function variants: 9 observed, 31.46 expected, observed/expected ratio (o/e) 0.29, 90% interval 0.17 to 0.5. The upper end of that interval is the gene's LOEUF score, 0.5, which puts it in group 2 of 6, group 1 being the genes least tolerant of losing a copy. Missense variants: 201 observed, 321.88 expected, observed/expected ratio (o/e) 0.62, 90% interval 0.56 to 0.7. Synonymous variants: 105 observed, 112.48 expected, observed/expected ratio (o/e) 0.93, 90% interval 0.8 to 1.1.
Homologues: Orthologues: chimpanzee SRSF10 (100% identical), guinea pig SRSF10 (100% identical), mouse Srsf10 (100% identical), rat Srsf10 (100% identical), dog SRSF10 (99% identical), macaque SRSF10 (99% identical), pig SRSF10 (99% identical), rabbit SRSF10 (99% identical), tropical clawed frog srsf10 (76% identical), zebrafish srsf10b (58% identical). Paralogues in human: SRSF12 (55% identical), SRSF2 (39% identical), SRSF8 (34% identical).
Diseases named in the same sentence as SRSF10 in open-access papers:
SRSF10 is named in the same sentence as 41 diseases in open-access papers, as found by Europe PMC text mining. Sharing a sentence is not in itself a finding about the gene and the disease. The quoted sentences say what the papers report.
breast carcinoma (7 papers, 2020 to 2025). "In breast cancer cells, elevated intracellular lactate levels cause H3 K18 la enrichment in the − 70 to + 3 promoter area, which increases c-Myc expression; this, in turn, controls SRSF10 to affect alternative splicing of MDM4 and Bcl-x." (PMID 40295451, 2025). "Conversely, inhibiting glycolysis rates, reducing lactate levels and lactylation, can successfully inhibit the c‐Myc‐SRSF10 axis and impede breast cancer progression." (PMID 40443721, 2025). "According to their findings, serine/arginine splicing factor 10 (SRSF10) expression is upregulated by c-Myc to promote alternative splicing in breast cancer cells." (PMID 40295451, 2025). "c‐Myc drives the alternative splicing of genes MDM4 and Bcl‐x in breast cancer cells by transcriptionally upregulating serine/arginine‐rich splicing factor 10 (SRSF10), thereby accelerating breast cancer progression." (PMID 40443721, 2025). "Additionally, the interaction between c-Myc and SRSF10 has been shown to promote proliferation of breast cancer cells." (PMID 39286028, 2024). "Therefore, chemotherapeutic therapies that reduce the glycolytic rate may limit the growth of breast cancer by blocking the c-Myc-SRSF10 axis." (PMID 40295451, 2025). "Additionally, among splicing regulators frequently altered in breast cancers (in >5% of tumors), we found different members of SR protein family (such as SRSF1, SRSF2, SRSF3, SRSF4, SRSF6, SRSF9, SRSF10, SRSF11) with at least one predicted binding motif in the CD44 v10 region." (PMID 33143085, 2020). "Whether SRSF10 plays a similar role in breast cancer or not requires more experimental confirmation." (PMID 32190687, 2020).
colon cancer (7 papers, 2017 to 2024). "While SRSF10 has been reported in different model systems including colon cancer, cervical cancer for its role in the regulation of AS, its deregulation in HNC has remained to be elucidated, which is the sixth most common cancer worldwide." (PMID 34616729, 2021). "Similarly, SRSF10 is involved in RNA splicing and as a regulator of oncogenesis in hepatocellular carcinoma, as well as cervical and colon cancer." (PMID 38157275, 2024). "Moreover, SRSF10 promotes the splicing of transcription factor BCLAF1 to facilitate the tumorigenesis of colon cancer." (PMID 32600379, 2020). "Overexpression of SRSF10 promotes the development of colon cancer via regulating BCLAF1 splicing." (PMID 32600379, 2020).
hepatocellular carcinoma (7 papers, 2022 to 2025). A malignant tumor that arises from hepatocytes. "Consistent with this view, BCLAF1 has been implicated in angiogenesis, and both BCLAF1 and SRSF10 facilitate metastasis of hepatocellular carcinoma cells." (PMID 38753413, 2024). "In the future, targeted inhibitors against SRSF10 will be found to potentially inhibit M2 macrophage polarization, thereby enhancing the efficacy of anti-PD-1 hepatocellular carcinoma therapy." (PMID 40129567, 2025). "1C8 also affects SRSF10-dependent SREK1 alternative splicing in a hepatocellular carcinoma cell line, and inhibits the growth of Hep3B cells." (PMID 38753413, 2024). "In hepatocellular carcinoma (HCC), lactate accumulation induces H3K18la, which further upregulates SRSF10, indirectly increasing GLUT1, HK1, and LDHA expression, thereby sustaining lactate accumulation and histone lactylation." (PMID 40859309, 2025). "1C8 reprograms the SRSF10-dependent alternative splicing of BCLAF1 and SREK1 in colorectal and hepatocellular carcinoma cell lines, respectively." (PMID 38753413, 2024). "Alternative splicing (AS) events are extensively involved in the progression of diverse tumors, but how serine/arginine-rich splicing Factor 10 (SRSF10) behaves in hepatocellular carcinoma (HCC) has not been sufficiently studied." (PMID 36539837, 2022).
glioma (6 papers, 2020 to 2025). A benign or malignant brain and spinal cord tumor that arises from glial cells (astrocytes, oligodendrocytes, ependymal cells). "The study of other splicing factors implicated in aberrant splicing indicated that SRSF10, which is upregulated in glioma-associated endothelial cells, contributes to this process by promoting the biogenesis of circular-ataxin 1 (circ-ATXN1) biogenesis." (PMID 39915450, 2025). "The potential function of SRSF10/circ-ATXN1/miR-526b-3p axis in glioma-associated endothelial cells (GECs) angiogenesis was further studied." (PMID 32600379, 2020). "SRSF10 also contributes to the development of gliomas, and controls the alternative splicing of WTAP, which is involved in the migration and invasion of cholangiocarcinoma cells." (PMID 38753413, 2024). "SRSF10 upregulates the production of a circular RNA (CIRC-ATXN1) that plays a role in glioma angiogenesis by sequestrating mir-526b-3p, which normally inhibits the expression of pro-angiogenic MMP2 and VEGFA." (PMID 36611187, 2023). "This study elaborated the critical regulatory effects of SRSF10/circ-ATXN1/miR-526b-3p pathway on glioma angiogenesis." (PMID 32600379, 2020). "As a result, knockdown of SRSF10 suppressed proliferation, migration and tube formation of GECs to inhibit glioma angiogenesis." (PMID 32600379, 2020). "We further investigated SRSF10/ circ-ATXN1/ miR-526b-3p axis on glioma angiogenesis, in order to provide new theoretical and experimental basis in regulating glioma angiogenesis." (PMID 32600379, 2020). "The function of SRSF10 in glioma angiogenesis is still unclear." (PMID 32600379, 2020). "In addition, SRSF10 may also involve in modulating circular RNA biogenesis to regulate glioma angiogenesis." (PMID 35296659, 2022). "Thus, we hypothesized that circ-ATXN1 was involved in SRSF10-mediated regulation on glioma angiogenesis." (PMID 32600379, 2020). "The knockdown of SRSF10 and circ-ATXN1 significantly reduced GEC proliferation, migration, and tube formation in vitro and reduced glioma angiogenesis in vivo." (PMID 39915450, 2025). "In summary, we discovered the molecular regulatory network in which SRSF10 facilitated circ-ATXN1 biogenesis and subsequently increased its binding with miR-526b-3p to inhibit the negative regulatory effect of miR-526b-3p on MMP2 and VEGFA in regulating glioma angiogenesis." (PMID 32600379, 2020).
cervical cancer (5 papers, 2020 to 2021). A primary or metastatic malignant neoplasm involving the cervix. "Accordingly, the silencing of E6/E7 mRNA was shown to cause downregulation of SRSF10 in cervical cancer as well as in cervical cancer cell line SiHa." (PMID 32596243, 2020). "Studies revealed that the splicing factor SRSF10 can mediate AS of IL1RAP to facilitate oncogenesis in cervical cancer." (PMID 32528230, 2020). "SRSF10, as a splicing factor, has been found playing important roles in colon and cervical cancer oncogenesis by mediating alternative splicing." (PMID 32190687, 2020). "As a splicing factor, SRSF10 mediates IL1RAP’s alternative splicing and promotes oncogenesis in cervical cancer." (PMID 32600379, 2020). "Similarly, the SRSF10 is increasingly overexpressed in CIN and cervical cancer cells." (PMID 32596243, 2020).
colorectal cancer (3 papers, 2018 to 2024). A primary or metastatic malignant neoplasm that affects the colon or rectum. "Splicing factor SRSF10 was reported to be involved in the mRNA splicing of BCLAF1 in colorectal cancer." (PMID 38340178, 2024). "SRSF10 can act as a sequence-dependent splicing factor to regulate the AS of BCLAF1 and mIl1RAP to promote the growth of cancer cells in colorectal cancer and cervical cancer." (PMID 35296659, 2022).
lung carcinoma (3 papers, 2018 to 2025). "Our results indicate that the CK1ε–SRSF10 axis regulates the alternative splicing of Bcl-x, and this axis is associated with the pathogenesis of lung cancer." (PMID 40701249, 2025). "Compared with cisplatin, a standard chemotherapeutic agent for lung cancer, silencing SRSF10, and CK1ε exhibited potent inhibitory effects on the growth of lung cancer." (PMID 40701249, 2025). "Depletion of SRSF10 significantly enhanced apoptosis in A549 cells, while CK1ε inhibitor SR3029 further potentiated the effect of SRSF10 knockdown on apoptosis in lung cancer cells." (PMID 40701249, 2025). "This study elucidates a novel mechanism by which the CK1ε–SRSF10 axis regulates Bcl-x alternative splicing and tumorigenesis in lung cancer." (PMID 40701249, 2025). "Treatment with SR3029 and knockdown of SRSF10 exerted a stronger inhibitory effect on the viability, proliferation, and colony formation in lung cancer cells." (PMID 40701249, 2025). "The xenograft model of lung cancer cells confirmed that pharmacological inhibition of CK1ε and the knockdown of SRSF10 synergistically inhibited tumor growth." (PMID 40701249, 2025). "We next evaluated the effect of CK1ε/SRSF10 axis on Bcl-x alternative splicing in lung cancer cells, the expression of SRSF10 was knocked down." (PMID 40701249, 2025). "Our studies showed that knockdown of SRSF10 could enhance apoptosis and inhibit the viability, proliferation, and clonogenic formation in lung cancer cells, while CK1 inhibitor SR3029 further potentiated the effect of silencing SRSF10 on lung cancer cells." (PMID 40701249, 2025). "In addition, we compared the effect of CK1ε or SRSF10 silencing with the standard therapeutic agent cisplatin on lung cancer in mice." (PMID 40701249, 2025). "Furthermore, depletion of SRSF10 markedly promoted apoptosis and inhibited the viability, proliferation, and colony formation in lung cancer cells." (PMID 40701249, 2025). "Taken together, these results imply that SRSF10 and CK1ε may play an important role in pathogenesis of lung cancer, and SRSF10 may be involved in the expression of Bcl-x splicing." (PMID 40701249, 2025). "Taken together, our results revealed a novel mechanism by which the CK1ε/SRSF10 axis regulates the alternative splicing of the Bcl-x precursor mRNA, which may be a potential therapeutic target for lung cancer." (PMID 40701249, 2025). "The administration of cisplatin and knockdown of SRSF10 or CK1ε effectively suppressed the growth of lung cancer without changes in body weight, while silencing SRSF10 exerted strongest inhibitory effect on tumor growth." (PMID 40701249, 2025). "Similarly, we identified several splicing proteins, such as SNRPD2, SNRPG, SNRPD3, HNRNPM, HNRNPH3, and SRSF10, in human breast and lung cancer TuNEPs but not in NETs." (PMID 40751052, 2025).
atherosclerosis (2 papers, 2014 to 2025). A disease characterized by the build-up of fatty material and calcium deposition in the arterial wall resulting in partial or complete occlusion of the arterial lumen. "In addition, by inferring PCL-responsive gene networks in early, mature and advanced atherosclerotic lesions, we identified key drivers specific for regression of early (PPARG), mature (MLL5) and advanced (SRSF10/XRN2) atherosclerosis." (PMID 24586211, 2014). "Our validation of stage-specific master regulators in the foam cell model of regression suggests that MLL5, SRSF10, and XRN2 will be useful targets for improving atherosclerosis regression after PCL in individuals with mature or even advanced lesions." (PMID 24586211, 2014). "In early lesions, PPARG was identified as a specific master regulator of the PCL-responsive atherosclerosis TF-regulatory network, whereas in mature and advanced lesions, the specific master regulators were MLL5 and SRSF10/XRN2, respectively." (PMID 24586211, 2014). "Both SRSF10 and XRN2 were specific master regulators for the advanced atherosclerosis network (P = 0.035, P = 0.040, respectively)." (PMID 24586211, 2014).
head and neck cancer (2 papers, 2021 to 2022). A primary or metastatic malignant neoplasm affecting the head and neck. "In Head and Neck Cancer, SRSF10 regulates the splice variants of BCL2 Like 1 and Pyruvate kinase M to promote tumorigenesis." (PMID 35296659, 2022). "Here, in this study, we report the frequent upregulation of SRSF10 (serine and arginine-rich splicing factor 10), a member of an expanded family of SR splicing factors, in the head and neck cancer (HNC) patients sample in comparison to paired normal tissues." (PMID 34616729, 2021).
lung carcinoids (2 papers, 2023 to 2025). "SRSF10 has been found to be highly expressed in lung carcinoids." (PMID 40701249, 2025). "In summary, our work primarily unveils a clear alteration of the splicing machinery in lung carcinoids that is linked to three specific factors, NOVA1, PRPF8 and SRSF10, which are differentially associated to pathological features, distinct profiles of splicing events, and key functional actions." (PMID 38049848, 2023).
nasopharyngeal carcinoma (2 papers, 2024 to 2025). A carcinoma arising from the nasopharyngeal epithelium. "For example, c-Myc, in combination with splicing factor 10 (SRSF10), can promote the transcription and back-splicing of CAMSAP1 precursor mRNA, leading to the proliferation and metastasis of nasopharyngeal carcinoma." (PMID 38926764, 2024).
steatosis (2 papers, 2022 to 2024). Increased lipid within the cytoplasm of cells. "Histologically, Srsf10-kd mice showed increased steatosis as determined by H&E and direct quantification of intrahepatic triglyceride content." (PMID 35293570, 2022).
carcinoids (1 paper, 2023). "In contrast, NOVA1 and SRSF10 expression were linked to a more limited number of splicing events, supporting the contention that these 3 altered factors may be involved in relevant but distinct functional roles in carcinoids." (PMID 38049848, 2023). "Inasmuch as the primary known role for NOVA1, PRPF8 and SRSF10 is their function as splicing factors, we aimed at examining their putative relationship with the alternative splicing profile in carcinoid cells." (PMID 38049848, 2023). "The presence of the selected splicing factors in carcinoids was further examined by IHC analysis, which confirmed that the protein of three splicing factors, NOVA1, PRPF8 and SRSF10 was detectable in tissue samples." (PMID 38049848, 2023).
colorectal tumors (1 paper, 2024). "While SRSF10 is overexpressed in high grade human colorectal tumors to promote production of the tumorigenic BCLAF-L splice variant, the genetic depletion of SRSF10 has little impact on the proliferation of HCT116 cells in culture." (PMID 38753413, 2024).
Ewing sarcoma (1 paper, 2020). A small round cell tumor that lacks morphologic, immunohistochemical, and electron microscopic evidence of neuroectodermal differentiation. "In this study, by employing multiple approaches, we have now identified several splicing factors (SRSF1, SRSF3, and SRSF10, hnRNPK, hnRNPM, and FUS) as regulators of DHX9 splicing in Ewing sarcoma cells." (PMID 32023846, 2020).
hepatitis B (1 paper, 2021). "Consistent with this hypothesis, we did observe changes in SR protein abundance, modification, and function upon GPS491 addition, in particular a reduction in SRSF10 function, which plays a critical role in HIV-1 and hepatitis B replication." (PMID 35062264, 2021).
liver disease (1 paper, 2022). "Collectively our work implicates dysregulated pre-mRNA polyadenylation in obesity-induced liver disease and uncovers a novel role for SRSF10 in this process." (PMID 35293570, 2022).
lung squamous cell carcinoma (1 paper, 2025). "The expression data of SRSF10 in 539 samples of lung squamous cell carcinoma (LUSC) along with 72 paired adjacent noncancerous tissues, and 594 samples of LUAD with 59 paired adjacent noncancerous tissues obtained from the TCGA database." (PMID 40701249, 2025).
Obesity (1 paper, 2022). Accumulation of substantial excess body fat. "To directly test this hypothesis in a pathophysiological context in vivo, we generated a loss-of-function model for Srsf10 in the liver and induced obesity using a high fat diet." (PMID 35293570, 2022). "Mechanistically, our work uncovers a novel role for SRSF10 in repressing cryptic intronic polyadenylation signals to maintain the expression of key metabolic genes, preventing the development of obesity-induced liver pathology." (PMID 35293570, 2022).
oral cancer (1 paper, 2026). "SRSF3, SRSF10, and SRSF11 show increased expression as the disease progresses, indicating their involvement in oral cancer progression." (PMID 41584036, 2026).
osteosarcoma (1 paper, 2024). A usually aggressive malignant bone-forming mesenchymal neoplasm, predominantly affecting adolescents and young adults. "We identified 6 splicing factor genes associated with the prognosis of osteosarcoma patients, namely SRSF1, SRSF4, SRSF5, SRSF7, SRSF8, and SRSF10." (PMID 39286028, 2024).